NHS (NHS actin remodeling regulator)
Description:
May function in cell morphology by maintaining the integrity of the circumferential actin ring and controlling lamellipod formation. Involved in the regulation eye, tooth, brain and craniofacial development.
Synonyms: CTRCT40; CXN
Tractability: Antibody: UniProt places it where antibodies can reach, with medium confidence; its Gene Ontology location is reachable by antibodies, with medium confidence.
Gene: Protein-coding gene on chromosome X (17,375,200 to 17,735,994, forward strand). Ensembl gene ENSG00000188158.
Subcellular location: Apical cell membrane (Isoform 1); Cell projection, lamellipodium; Cell junction, tight junction; Cell junction, focal adhesion; Cytoplasm (Isoform 3)
Subcellular location (Human Protein Atlas): Cell Junctions
Pathways (Reactome):
Signal Transduction: RAC1 GTPase cycle; RAC2 GTPase cycle; RAC3 GTPase cycle
Gene Ontology:
Biological process: cell differentiation; lens development in camera-type eye
Cellular component: cell junction; apical plasma membrane; bicellular tight junction; cytoplasm; focal adhesion; lamellipodium
Gene-disease validity (ClinGen):
ClinGen rates the evidence that NHS causes each of these diseases.
Nance-Horan syndrome (X-linked): Definitive. A syndrome characterized by the association in male patients of congenital cataracts with microcornea, dental anomalies and facial dysmorphism.
Homologues: Orthologues: chimpanzee NHS (98% identical), macaque NHS (96% identical), dog NHS (91% identical), guinea pig NHS (89% identical), mouse Nhs (89% identical), rabbit NHS (87% identical), rat Nhs (81% identical), pig NHS (78% identical), tropical clawed frog nhs (61% identical), zebrafish nhsb (47% identical), zebrafish nhsa (40% identical). Paralogues in human: NHSL1 (24% identical), NHSL2 (19% identical), NHSL3 (11% identical).
Diseases named in the same sentence as NHS in open-access papers:
NHS is named in the same sentence as 12 diseases in open-access papers, as found by Europe PMC text mining. Sharing a sentence is not in itself a finding about the gene and the disease. The quoted sentences say what the papers report.
cataract (2 papers, 2008 to 2022). Partial or complete opacity of the crystalline lens of one or both eyes that decreases visual acuity and eventually results in blindness. "For example, COL5A1 and NHS, both genes bearing endogenous CTG/CAG repeats, therefore potential silencing targets of the toxic siRNAs, are known causes of cataract." (PMID 36060259, 2022).
congenital cataract (2 papers, 2014 to 2020). "Combined with our previous studies, a genetic basis could be identified in 67.6% of families with congenital cataracts in our case series, in which mutations in genes encoding crystallins, genes encoding connexins, and NHS are responsible for 29.4%, 14.7%, and 11.8% of families, respectively." (PMID 24968223, 2014).
autism (1 paper, 2019). Persistent deficits in social interaction and communication and interaction as well as a markedly restricted repertoire of activity and interest as well as repetitive patterns of behavior. "Significantly greater than expected number of rare variants were detected in 5 of the 101 tested autism-linked genes: AUTS2, NHS, NSD1, SLC9A9, and VPS13B." (PMID 31134136, 2019). "Rare variant analysis on a cohort level confirmed the association of five genes with autism (AUTS2, NHS, NSD1, SLC9A9, and VPS13)." (PMID 31134136, 2019).
breast carcinoma (1 paper, 2020). "According to Kaplan–Meier plotter, low expression of NHS, THBS4, and SLITRK6 is associated with poor relapse-free survival (RFS) in breast cancer patients." (PMID 32679794, 2020).
melanoma (1 paper, 2024). A malignant, usually aggressive tumor composed of atypical, neoplastic melanocytes. "The X‐linked cancer‐related genes that have been associated with melanoma include ZNF280C, IL3RA, PNMA3, NHS, and FGD1." (PMID 38827026, 2024).
Nance-Horan syndrome (1 paper, 2020). "An interaction network analysis of the top 100 DM CpG sites showed five common regulator genes: nemo-like kinase (NLK), calcium/calmodulin-dependent protein kinase 1 (CAMKK1), lysophosphatidic acid receptor 2 (LPAR2), caspase 1 (CASP1), and Nance-Horan syndrome (NHS)." (PMID 32605309, 2020).
NHS also shares sentences with these, for which no sentence is quoted: cancer (1 paper); Intellectual disability (1); pancreatic adenocarcinoma (1); pancreatic cancer (1); scrapie (1); tumours (1).